BDNF (brain derived neurotrophic factor)
Diseases named in the same sentence as BDNF in open-access papers (continued):
Sharing a sentence is not in itself a finding about the gene and the disease.
depression (continued). "Increased BDNF expression has been associated with neuroplasticity impairment, one of the pathogenesis of depression." (PMID 33374661, 2020). "The presence of rs6265 polymorphism is associated with low levels of BDNF expression and altered function in patients with depression." (PMID 33269104, 2020). "BDNF levels were significantly lower in patients with major depressive disorder (MDD) than the control group, and recovery from depression after antidepressant treatment was associated with normal serum levels of BDNF in patients with MDD." (PMID 32570775, 2020). "The Val66Met polymorphism within the pro-domain of BDNF has been associated with a variety of psychiatric disorders including depression, a symptom that is often co-morbid with cancer-related fatigue." (PMID 32848137, 2020). "Their alterations increased the risk for depression and worsened the response to antidepressants, of which, the brain-derived neurotrophic factor (BDNF) was heatedly investigated." (PMID 33117794, 2020). "In major depression disorders, serum BDNF level has been used as a diagnostic parameter and low levels of BDNF were found in the serum of depression patients." (PMID 33364963, 2020). "It is also important to notice that the rs6265 Met allele of the BDNF Val66Met polymorphism has been implicated as a significant moderator of the relationship between stress and depression." (PMID 33269104, 2020). "Chronic stress and depression are associated with reduced BDNF synthesis and decreased TrkB signaling in the hippocampus and cerebral cortex." (PMID 33109198, 2020). "Similar to depression, some researchers observed an association of serum BDNF levels with anxiety and stress." (PMID 32085720, 2020). "The present study focuses on association of SLC1A3 C3590T, C869G and BDNF G196A in case control studies with stress and depression in an eastern Indian population." (PMID 32171272, 2020). "An increase of circulating BDNF was associated with depression familiarity mixed state episodes, and to ADs administration." (PMID 32517269, 2020). "The important finding was that postpartum female mice showed higher susceptibility to SCUS-induced depression-related behavior and that mPFC-specific BDNF-knockout induced differential behavioral phenotypes in virgin and postpartum female mice." (PMID 32532322, 2020). "Despite multiple variables influencing serum BDNF, it has gained interest as a biomarker in mental health, and have been implicated in various psychopathologies such as depression, schizophrenia and Alzheimer’s disease." (PMID 32575733, 2020). "SLC1A3 (C3590T and C869G) and BDNF (G196A) are associated with stress and depression in adolescent population of eastern Uttar Pradesh (India), a control-case association study has been undertaken." (PMID 32171272, 2020). "Methylation of BDNF loci was found to be associated with increased rates of depression, reported feelings of hopelessness and impulsivity." (PMID 30968208, 2020). "BDNF is one of the most inspiring molecules to better understand the disadvantageous synaptic learning underlying the etiology of depression, accompanied by the decline in the rate of adult neurogenesis and in spine densities." (PMID 33096634, 2020). "Decreased BDNF levels and mutations in genes associated with BDNF signaling have been associated with hippocampal dysfunction, memory impairment, increased risk for depression, schizophrenia, and anxiety." (PMID 32655354, 2020). "We observed a significant association between BDNF gene variant rs6265 and the severity of depression in newly admitted, antidepressant treatment-free, depressed patients." (PMID 32116853, 2020). "Depression-associated variables such as depressed mood also moderated the relationship between BDNF Val66Met and executive functions in previous work." (PMID 32002751, 2020).
depression (continued). "BDNF is also found to be associated with the pathogenesis of several neuropsychiatric and neurodegenerative disorders, including major depressive disorder (MDD), bipolar disorder (BD), schizophrenia, Parkinson disease, Alzheimer disease, and epilepsy." (PMID 33152026, 2020). "BDNF deficiencies have been linked to mental disorders such as depression, bipolar disorder, and schizophrenia." (PMID 32595741, 2020). "An inflammatory state can contribute to the development and progression of depression pathology, influencing alterations of the neuroplasticity caused by reduced BDNF expression, activity, and affinity to a receptor." (PMID 33213019, 2020). "BDNF is an important factor in hippocampal synaptic plasticity and BDNF deficits are directly implicated in clinical depression." (PMID 33109198, 2020). "Further studies of genotype are needed, since the BDNF Met allele is a risk factor for several other neuropsychiatric disorders, including depression, schizophrenia, Parkinson, and Alzheimer’s disease." (PMID 30356121, 2020). "Brain-derived neurotrophic factor (BDNF) deficiency contributes to the pathophysiology of depression." (PMID 32457610, 2020). "A meta-analysis reported a strong evidence of an association between depression and a decrease in BDNF levels (p < 6.8 × 10−8)." (PMID 33584494, 2020). "Some studies suggested a role of IL-1β in reducing BDNF in patients with depression, indicating that an increase in IL-1β concentrations was associated with a decrease in BDNF concentrations." (PMID 32517269, 2020). "This outcome warrants further investigation into the effects of DHM on alcohol withdrawal and depression, as reduced serum BDNF levels are associated with severe alcohol withdrawal and relapse." (PMID 32267550, 2020). "Several preclinical and clinical data reported that an increase in ADMA infusion alone causes a marked reduction in serum BDNF levels leading to behavioral changes and depression of CKD in 11 hemodialyzed patients as well as in nephrectomized rats." (PMID 33353117, 2020). "Smoking and diabetes are accompanied by a decreased BDNF concentration in blood and both are independent risk factors for depression." (PMID 33255237, 2020). "Animal studies reveal an association between BDNF expression in hippocampus and intensity of the post-stroke depression." (PMID 31701356, 2020). "BDNF transcription through its multiple promoters, its trafficking, and its secretion have all been implicated in the onset and development of depression." (PMID 32492978, 2020). "Considering the importance of neurotrophins for brain health maintenance, research has linked lower concentrations of BDNF with neurodegenerative diseases and depression." (PMID 31627408, 2019). "Studies have shown that BDNF methylation, which decreases BDNF transcription, is associated with depressive-like behavior in mice and depression in humans." (PMID 31572245, 2019). "The P-CREB, as a transcription factor, regulates over hundred target genes, especially BDNF, implicated in neuronal regeneration, development, survival, and excitability, addiction, depression and cognition." (PMID 31531058, 2019). "Several in vitro and in vivo studies indicate that neuroinflammatory processes, which are widely linked with the development of depression, affect BDNF expression." (PMID 31053872, 2019). "Patients with borderline personality disorder who underwent behavioral dialectical psychotherapy had a change of methylation of the BDNF gene at the end of the treatment that was associated with change scores in depression, hopelessness, and impulsivity." (PMID 31024364, 2019). "Three SNPs, including rs6265, were found to modify the association between late-life depression and BDNF exon I promoter methylation levels." (PMID 31027379, 2019). "Low circulating levels of BDNF have been associated with a plethora of diseases such as obesity, type 2 diabetes, depression, and cognitive impairments." (PMID 31649549, 2019).
depression (continued). "In a follow-up study of patients with post stroke depression, a higher BDNF methylation level was associated with prevalence, persistence, and incidence of depression, and with worsening depressive symptoms over follow-up." (PMID 31027379, 2019). "The serum protein levels of the BDNF pathway have been implicated in depression and antidepressant treatment efficacy." (PMID 31098654, 2019). "Here we investigated the importance of BDNF signalling in the inflammatory, survival and apoptotic processes of diabetes-associated depression, and suggest novel targets for clinical therapy." (PMID 31053872, 2019). "Brain-derived neurotrophic factor (BDNF) has been associated with the psychopathology of both major depressive disorder (MDD) and schizophrenia (SZ)." (PMID 30794585, 2019). "Serum levels of BDNF were independently associated with depression in acne vulgaris patients with depression." (PMID 31234814, 2019). "After the combination and activation of TrkB, BDNF was thought to underlie OFG for the treatment of depression." (PMID 30940777, 2019). "In patients with breast cancer after mastectomy, a higher BDNF methylation level was associated with the diagnosis of depression and with more severe symptoms throughout the study period." (PMID 31027379, 2019). "BDNF/NTRK2 signaling has been linked to both the pathophysiology of depression and the mode of action of antidepressants." (PMID 30765816, 2019). "The protein expressions of PKA, CREB, and BDNF in hippocampus were detected for the underlying mechanism of OFG-mediated depression." (PMID 30940777, 2019). "The LPS-induced depression model is a well-known acute depression model, in which microglia-secreting cytokines activated by LPS cause depressive behavior by decreasing BDNF expression." (PMID 31771312, 2019). "The gene encoding the brain-derived neurotrophic factor (BDNF) has also been closely linked to depression." (PMID 31440532, 2019). "In geriatric patients with depression, a higher BDNF methylation level was associated with both the prevalence and incidence of depression diagnosis, as well as symptom severity." (PMID 31027379, 2019). "Chronic high concentrations of GC, associated with down-regulated BDNF expression in hippocampus, can cause anxiety and depression-like behavior, which in turn affects neuronal plasticity, learning and memory, and severe neuronal injury." (PMID 31888678, 2019). "BDNF/TrkB pathway is one of a few best-characterized signaling pathways underlying the pathophysiology of chronic stress and depression." (PMID 31057357, 2019). "Trophic factors, especially BDNF, was suggested to be associated with the development of depression, and thus responsible for the antidepressant activity in preclinical and clinical studies." (PMID 31540539, 2019). "BDNF is a neurotrophic factor which has been shown to be associated with post-TBI depression and cognitive dysfunction." (PMID 31541141, 2019). "Three single nucleotide polymorphisms, including rs6265, were found to modify the association between depression and BDNF promoter I methylation." (PMID 31027379, 2019). "For example, the BDNF val66met polymorphism has been found to modify associations between childhood maltreatment and incident depression in children, and between recent stressful life events and incident depression in elders." (PMID 31887219, 2019). "The role of a single nucleotide polymorphism in the coding region of BDNF gene, BDNF rs6265 has been investigated in several neuropsychiatric disorders including major depressive disorder." (PMID 30677092, 2019). "By contrast, the same data pointed to heightened risk of depression for carriers of BDNF Met and 5-HTTLPR-L alleles with histories of childhood abuse." (PMID 31440532, 2019). "Our evidence suggested that EEA treatment increased BDNF gene expression, contributing to the regulation of depression-like behaviors caused by neuroinflammation." (PMID 31251788, 2019).
depression (continued). "Several studies support the role of reduced BDNF activity in inflammatory cytokine-associated depression." (PMID 31251788, 2019). "As BDNF appears to be a key molecule in neuronal plasticity and neuronal atrophy in the hippocampus has been linked to treatment outcome in depression, our findings will be reviewed in the context of hippocampal atrophy." (PMID 31127089, 2019). "BDNF has been associated with improvements in depression, which is one of the common comorbid psychiatric disorders in CFS." (PMID 31709006, 2019). "BDNF single nucleotide polymorphism (val66met), however, is associated with the severity of depression in patients." (PMID 30117106, 2019). "Here, for the first time, we demonstrated changes in both forms of hippocampal BDNF in diabetes-associated depression." (PMID 31053872, 2019). "The P-CREB, as a transcription factor, adjusts over hundred genes, mainly BDNF which is strongly associated in neuronal regeneration, development, survival, excitability, addiction, depression, and cognition." (PMID 31579440, 2019). "Downregulation of BDNF was found to be associated with Alzheimer's disease, Parkinson's disease, schizophrenia, and possibly depression." (PMID 31281833, 2019). "Our literature reviews implied that BDNF have been associated with pathophysiology of depression in patients with poststroke depression, systemic lupus erythematosus, multiple sclerosis, and postpartum depression." (PMID 31234814, 2019). "Presence of the met allele in the val66met BDNF polymorphism in conjunction with ELS predicted greater depression and anxiety symptoms, although this was specifically mediated through diminished left prefrontal cortex brain volume and heightened heart rate." (PMID 31428006, 2019). "Reductions in hippocampal BDNF are seen in human depression and associated with the BDNF-Val66Met and 5-HTTLPR risk alleles and reduced 5-HT1A receptor function." (PMID 31114473, 2019). "BDNF, an important regulating protein, is reported to not only contribute to depression, but decrease during chronic depression, causing a vicious circle and deteriorating depression over time." (PMID 31491962, 2019). "BDNF has been extensively studied for its vital role in neuronal function and its causal link to depression." (PMID 32009871, 2019). "In a prospective study, MD adherence was found to be significantly associated with higher plasma levels of BDNF and a lower risk of depression." (PMID 30934558, 2019). "An alternative strategy to directly reverse BDNF deficiency is intranasal administration of a viral brain-permeant BDNF construct, which reversed the depression phenotype in mice following chronic mild stress." (PMID 31114473, 2019). "Deficiency of BDNF–TrkB–CREB function induces susceptibility to depression in rodents, while administration of BDNF–TrkB–CREB elicits antidepressant-like effects in animal models of depression." (PMID 31572200, 2019). "Neurotrophin theory of depression suggests that decreased BDNF level can cause reduced hippocampal neural proliferation, which results in the pathophysiology of depressive disorder including cognitive deficits." (PMID 31193084, 2019). "Exposure to them can cause cognitive impairment and depressive disorders through an effect on Brain-derived neurotrophic factor (BDNF) which is an important biomarker of pregnancy." (PMID 31199848, 2019). "In patients with acute coronary syndrome evaluated for depressive disorder, a higher BDNF methylation level was associated with prevalent depressive disorder at baseline and with its persistence at follow-up." (PMID 31027379, 2019). "In a study using buccal tissues of geriatric patients with MDD, DNA methylation levels of both BDNF promoters I and IV were associated with depression at baseline, and chronic late-life depression over the 12-year follow-up period." (PMID 31027379, 2019).
depression (continued). "In patients after acute coronary syndrome, increased BDNF methylation was associated with that finding that escitalopram was more effective than placebo for treating depressive disorder, and this effects lead to prevent persistent depressive disorder." (PMID 31027379, 2019). "It is important to notice that the disruption of BDNF/TrkB signaling pathway and impairment of neuronal plasticity have been implicated in the pathogenesis of depressive disorders." (PMID 32009956, 2019). "And a previous study suggested differential diagnostic properties of BDNF expression that mature BDNF is representative for depressive disorders and proBDNF is for bipolar diseases." (PMID 31199848, 2019). "Disruption of BDNF function is implicated in the pathology underlying numerous psychiatric disorders, ranging from schizophrenia and bipolar disorder to depression." (PMID 29867393, 2018). "It has been shown that there is an association of BDNF DNA methylation and reduced WM integrity in the anterior corona radiata in major depression." (PMID 29636708, 2018). "Taken together, these data suggest that the both NF-κB signaling pathway and the loss of microglia associated BDNF-CREB signaling pathway play an important role in the comorbidity of depression and chronic pain." (PMID 30356873, 2018). "An 11% volumetric decrease of the hippocampal region (a significant reduction that is comparable to that associated with diseased conditions such as major depression) has been associated with the BDNF Met allele carriage in healthy subjects." (PMID 29896439, 2018). "A meta-analysis of four studies including 499 stroke patients revealed that significant decrease in serum BDNF concentrations in the early period after stroke predisposed to the development of depression." (PMID 30061860, 2018). "We also found that improvements in depression and sleep quality were associated with an increase in plasma BDNF concentration following exercise, providing a potential biological marker for treatment outcome." (PMID 29559928, 2018). "In our studies of the BDNF Val66Met polymorphism and major depression, we found that Met carriers have an increased risk of geriatric depression, but not non-geriatric depression." (PMID 29867348, 2018). "Brain-derived neurotrophic factor (BDNF), a neurotrophin involved in neural development and adult brain plasticity, has been associated with stress response, depression and anxiety." (PMID 30347685, 2018). "Prior studies have found that decreased serum BDNF levels are associated with perceived stress, depression, or sleep disturbances in humans." (PMID 29944703, 2018). "Brain-derived neurotrophic factor (BDNF) gene expression in blood was found to be negatively associated with depression score (HAMD), and Bdnf/trkB signaling was reduced in the hippocampus of genetic model of vulnerability to stress-induced depression." (PMID 30042304, 2018). "Another important mediator between microglia and neurons is BDNF, which has also been linked to depression." (PMID 30319362, 2018). "Low levels of BDNF have been associated with anxiety and aggressive behavior in mice and with anxiety and depression in humans." (PMID 30618659, 2018). "Given the known role of BDNF in the pathophysiology and treatment of depression, large trial did find a positive relationship between ketamine effects and peripheral BDNF levels and a polymorphism of the BDNF gene." (PMID 30197765, 2018). "The findings were replicated by a recent meta-analysis of 31 studies, involving of 21,060 participants, providing further evidence for an interaction between the BDNF Val66Met polymorphism and life stress in depression." (PMID 29867348, 2018). "Brain‐derived neurotrophic factor (BDNF) has been associated with depression and its treatment response." (PMID 30273985, 2018). "The BDNF/TrkB system has been implicated in the pathophysiology of a number of psychiatric disorders, such as schizophrenia, depression, and PTSD." (PMID 30079015, 2018).